ZNF608 (zinc finger protein 608)
Description:
Transcription factor, which represses ZNF609 transcription.
Synonyms: KIAA1281; DKFZp434M098; NY-REN-36
Tractability: PROTAC: UniProt records ubiquitination sites on it; ubiquitination databases record sites on it; its protein half-life has been measured.
Gene: Protein-coding gene on chromosome 5 (124,636,913 to 124,748,807, reverse strand). Ensembl gene ENSG00000168916.
Subcellular location (Human Protein Atlas): Nucleoplasm; Mitochondria
Gene Ontology:
Biological process: negative regulation of transcription by RNA polymerase II; regulation of transcription by RNA polymerase II
Cellular component: nucleus
Genetic constraint (gnomAD): Loss-of-function variants: 11 observed, 112.88 expected, observed/expected ratio (o/e) 0.0974, 90% interval 0.06 to 0.16. The upper end of that interval is the gene's LOEUF score, 0.16, which puts it in group 1 of 6, group 1 being the genes least tolerant of losing a copy. Missense variants: 1,706 observed, 1,979.7 expected, observed/expected ratio (o/e) 0.86, 90% interval 0.83 to 0.9. Synonymous variants: 732 observed, 757.64 expected, observed/expected ratio (o/e) 0.97, 90% interval 0.91 to 1.03.
Homologues: Orthologues: chimpanzee ZNF608 (99% identical), macaque ZNF608 (99% identical), mouse Zfp608 (93% identical), rat Zfp608 (92% identical), guinea pig ZNF608 (79% identical), tropical clawed frog znf608 (75% identical), rabbit ZNF608 (65% identical), Drosophila melanogaster sbb (26% identical). Paralogues in human: ZNF609 (42% identical).
Diseases named in the same sentence as ZNF608 in open-access papers:
ZNF608 is named in the same sentence as 11 diseases in open-access papers, as found by Europe PMC text mining. Sharing a sentence is not in itself a finding about the gene and the disease. The quoted sentences say what the papers report.
ovarian carcinoma (2 papers, 2016 to 2019). A malignant neoplasm originating from the surface ovarian epithelium. "Of the 19 predicted miR-21-3p target genes analyzed, only three genes (RBPMS, RCBTB1 and ZNF608) were confirmed as miR-21-3p target genes in ovarian cancer cells." (PMID 27166999, 2016). "In addition, we identified RBPMS, RCBTB1 and ZNF608 as targets of miR-21-3p in cisplatin-resistant ovarian cancer cells." (PMID 27166999, 2016). "Moreover, proliferation and invasion of ovarian cancer cells could be impeded by inhibiting microRNA-21-associated target genes that included RBPMS, RCBT1 and ZNF608." (PMID 31084621, 2019). "A2780 ovarian cancer cells expressed lower levels of miR-21-3p and higher levels of RBPMS, RCBTB1, and ZNF608 as compared to A2780CP20 cells." (PMID 27166999, 2016).
allergic rhinitis (1 paper, 2025). Inflammation of the nasal mucous membranes caused by an IgE-mediated response to external allergens. "Joint effect and stratification analysis of wPRS based on five susceptibility SNPs in ZNF608 by with the risk of allergic rhinitis." (PMID 40765419, 2025). "The wPRS showed a notable combined risk effect of SNPs located in ZNF608 on susceptibility to HDM‐induced allergic rhinitis (OR = 1.40, 95% CI = 1.18–1.65, p = 1.18 × 10−4)." (PMID 40765419, 2025). "In summary, we conducted a genome‐wide gene association analysis and reported the genetic variants of key gene ZNF608 associated with risk of HDM‐induced allergic rhinitis." (PMID 40765419, 2025). "These indicated that five SNPs might modulate the expression of ZNF608, affecting immune cell states and perturbations in the immune system thus increasing the risk of allergic rhinitis and the occurrence of nasal symptoms." (PMID 40765419, 2025). "Although no significant eQTL signals were observed in immune cells for rs10067299, rs6866116 and rs79679768, they may modulate ZNF608 through other pathways to participate in susceptibility to allergic rhinitis." (PMID 40765419, 2025). "While our study demonstrates a statistically significant association between ZNF608 and allergic rhinitis, the sample size may limit detection of weaker genetic effects." (PMID 40765419, 2025). "In this study, we first performed a GWGAS study based on genomic data and identified the key gene ZNF608 associated with the susceptibility to HDM‐induced allergic rhinitis in Chinese individuals, validated by differential mRNA expression analysis based on transcriptome data." (PMID 40765419, 2025). "Therefore, to further investigate the role of the cumulation effect of ZNF608 genetic variants on allergic rhinitis, we constructed a wPRS and our results indicated that wPRS showed a 1.40‐fold per standard deviation (SD) increase in risk of HDM‐induced allergic rhinitis." (PMID 40765419, 2025). "Subsequently, we bioinformatically analyzed the transcriptome of nasal epithelial cells and observed that ZNF608 was upregulated in patients with allergic rhinitis than that in controls, consistent with the result from GWGAS (p = 0.041)." (PMID 40765419, 2025). "Considering the importance of genetic factors in HDM‐induced allergic rhinitis, we further aimed to identify potentially functional SNPs in the ZNF608 for deep exploration of the genetic etiology of allergic rhinitis." (PMID 40765419, 2025). "To elucidate the biological pathway regulated by ZNF608 in HDM‐induced allergic rhinitis, we further conducted a competitive gene‐set analysis by MAGMA." (PMID 40765419, 2025). "Since allergic rhinitis was convinced to be an immune‐related disease, we primarily focused on immunologic signature gene sets and included 64 pathways harboring ZNF608 manually." (PMID 40765419, 2025). "Independent replication in larger cohorts, combined with mechanistic studies, will be essential to validate these findings and elucidate ZNF608's role in allergic rhinitis." (PMID 40765419, 2025). "In our study, we further performed a logistic regression analysis and identified five associations between SNPs in ZNF608 and susceptibility to HDM‐induced allergic rhinitis." (PMID 40765419, 2025). "Additionally, both rs6862252 G allele and rs10042766 T allele elevated the expression of ZNF608 involving in state and perturbation of immune cells, such as B cell, T cell, and dendritic cell, contributing to HDM‐induced allergic rhinitis." (PMID 40765419, 2025). "ZNF608 was identified as the key gene involving HDM‐induced allergic rhinitis risk (p = 1.23 × 10−6), which was highly expressed in nasal epithelium cells of allergic rhinitis patients (p = 0.041)." (PMID 40765419, 2025). "These enriched gene sets indicated that ZNF608 might play an important role in the state and perturbation of immune cells involving allergic rhinitis." (PMID 40765419, 2025).
allergic rhinitis (continued). "This study highlights the key gene ZNF608 of HDM‐induced allergic rhinitis, which may lay the groundwork for risk assessment and early diagnosis of allergic rhinitis." (PMID 40765419, 2025). "It indicated that ZNF608 might be regulated by rs6862252 and rs10042766 within the immune microenvironment to contribute to allergic rhinitis." (PMID 40765419, 2025). "Association between 16 SNPs in ZNF608 after LD clumping and HDM‐induced allergic rhinitis risk." (PMID 40765419, 2025). "However, biological experiments for detailed mechanisms in immune cells were not further investigated in our study, which might help to elucidate the immune pathogenesis of ZNF608 in allergic rhinitis." (PMID 40765419, 2025). "We next conducted a gene‐set analysis focused on immune‐related pathways harboring key gene ZNF608 on HDM‐induced allergic rhinitis in this study, which highlighted the immunoregulatory role of ZNF608 in immune cells contributing to allergic rhinitis, such as T cell and dendritic cells (DCs)." (PMID 40765419, 2025).
asthma (1 paper, 2025). "Previous studies have shown that male‐specific polymorphisms in ZNF608 are associated with asthma‐COPD phenotype." (PMID 40765419, 2025).
breast carcinoma (1 paper, 2021). "Of the remaining 12 genes, seven (A4GALT, C2ORF74, HRCT1, ZC4H2, ZNF512, ZNF655, and ZNF608) show similar relative expression profiles in large patient samples and other breast cancer cell lines thereby giving insight into predicted role of H3K4me3 mediated gene regulation via the miRNA-mRNA axis." (PMID 34261302, 2021).
epilepsy (1 paper, 2025). A brain disorder characterized by episodes of abnormally increased neuronal discharge resulting in transient episodes of sensory or motor neurological dysfunction, or psychic dysfunction. "For example, APBB2 was reported to be associated with aging, ZNF608 with preclinical AD, ARID4A and ARVCF with neuropsychiatric diseases, CNN3 with epilepsy, and BTBD1O with ALS." (PMID 40725187, 2025).
schizophrenia (1 paper, 2022). A major psychotic disorder characterized by abnormalities in the perception or expression of reality. "Some of the connected genes like PRKCZ, SHANK2, ZNF608, and PRDM16 were also identified as schizophrenia risk factors." (PMID 36259657, 2022).
ZNF608 also shares sentences with these, for which no sentence is quoted: Alzheimer disease (1 paper); Obesity (1); respiratory diseases (1); tumor (1); type-2 diabetes (1).